GYS1 (glycogen synthase 1)
Diseases named in the same sentence as GYS1 in open-access papers (continued):
Sharing a sentence is not in itself a finding about the gene and the disease.
psoriasis (3 papers, 2023 to 2025). An autoimmune condition characterized by red, well-delineated plaques with silvery scales that are usually on the extensor surfaces and scalp. "The identified hub genes, particularly GYS1 and SLC3A2, represent potential biomarkers and therapeutic targets, offering new insight into the complex molecular landscape of psoriasis." (PMID 41224720, 2025). "Then, 5 potential hub genes (SOD2, PGD, PPIF, GYS1, AHCY) of psoriasis were identified by protein–protein interaction (PPI) networks using Metascape database." (PMID 36890558, 2023). "Together, the 5 hub genes (SOD2, PGD, PPIF, GYS1 and AHCY) play pivotal roles in the development of psoriasis." (PMID 36890558, 2023). "We found that SOD2, PGD, PPIF, GYS1 and AHCY are five hub genes in PPI networks, indicating the potential role in the psoriasis initiation and progression." (PMID 36890558, 2023). "GYS1 and SLC3A2 were highly expressed in epidermal cells from psoriatic lesions, aligning with previous reports of keratinocyte metabolic reprogramming in psoriasis." (PMID 41224720, 2025). "Venn diagram analysis revealed four overlapping genes, SLC3A2, GYS1, FLNA, and FLNB, which may serve as core candidates linking disulfidptosis to the molecular mechanisms of psoriasis." (PMID 41224720, 2025). "Five potential hub genes of psoriasis were obtained, including SOD2, PGD, PPIF, GYS1 and AHCY." (PMID 36890558, 2023). "However, the potential role of PGD, PPIF, GYS1 and AHCY has not been explored in psoriasis." (PMID 36890558, 2023).
renal carcinoma (3 papers, 2020 to 2025). A carcinoma arising from the epithelium of the renal parenchyma or the renal pelvis. "Since ccRCC is the most common lethal subtype accounting for renal carcinoma with unfavorable outcome compared with papillary renal cell carcinoma, and chromophobe renal carcinoma, it is essential to examine the clinical significance of GYS1 in large human samples." (PMID 32802186, 2020). "In the case of renal cancer, GYS1 interacts with RPS27A and forms a complex of GYS1/RPS27A that can increase the nuclear transfer of p65." (PMID 39014491, 2024).
acute myeloid leukemia (2 papers, 2020 to 2024). Acute myeloid leukemia (AML) is a group of neoplasms arising from precursor cells committed to the myeloid cell-line differentiation. "Overexpression of GYS1 was associated with adverse outcome in acute myeloid leukemia 19 and non-small cell lung cancer 20 in a small cohort of patients." (PMID 32802186, 2020). "Research indicates that the elevated expression of GYS1 is linked to unfavorable prognosis in acute myeloid leukemia (AML) and myelodysplastic syndrome (MDS)." (PMID 39000261, 2024).
cardiac arrest (2 papers, 2023). Cessation of breathing and/or cardiac function. "Furthermore, GYS1 deficiency compromises the cardiac ability to pump blood and increases the risk of cardiac arrest and sudden death during exercise." (PMID 37239976, 2023).
glycogen storage disease type 0b (2 papers, 2023). "GSD Type 0, also known as Glycogen synthase deficiency (Muscle glycogen synthase deficiency (encoded by GYS1) and liver glycogen synthase deficiency (encoded by GYS2))." (PMID 37601653, 2023). "Moreover, patients with glycogen storage disease type 0b caused by congenital GYS1 deficiency show increased mitochondrial proliferation and mitochondrial abnormalities in their muscle biopsies." (PMID 37280675, 2023).
glycogen synthase deficiency (2 papers, 2020 to 2023). "On a patient with muscle-specific glycogen synthase deficiency, type I fibers predominated, glycogen deficiency and increased mitochondria, and identified homozygosity for a 2 bp deletion in the GYS1 gene." (PMID 32258109, 2020). "GSD type 0 is caused by mutations in the GYS1 gene, leading to muscle glycogen synthase deficiency, and mutations in the GYS2 gene, leading to liver glycogen synthase deficiency." (PMID 37601653, 2023).
hypertrophic cardiomyopathy (2 papers, 2008 to 2024). A condition in which the myocardium is hypertrophied without an obvious cause. "This study revealed the potential relationship between disulfidptosis and hypertrophic cardiomyopathy and put forward a predictive model containing disulfidptosis-associated genes (DRGs) of GYS1, MYH10, PDMIL1, SLC3A2, CAPZB, showing excellent performance by SVM machine learning model." (PMID 39701955, 2024).
leukemia (2 papers, 2018 to 2019). A malignant (clonal) hematologic disorder, involving hematopoietic stem cells and characterized by the presence of primitive or atypical myeloid or lymphoid cells in the bone marrow and the blood. "Similar to our results, GYS1 knockdown also reduced the tumor growth of leukemia cells transplanted in SCID mice." (PMID 30100905, 2018).
Sepsis (2 papers, 2024 to 2025). Sepsis is defined as life-threatening organ dysfunction caused by a dysregulated host response to infection. "Expression of glycogen synthase 1 (Gys1) was upregulated in acute and prolonged sepsis, whereas expression of regulator glycogen synthase kinase (Gsk3b) or glycogen phosphorylase (Pygb) were not affected." (PMID 39821755, 2025). "The six intersection disulfidptosis‐related genes including LRPPRC, SLC7A11, GLUT, MYH9, NUBPL and GYS1 exhibited higher predictive ability for sepsis with an accuracy of 99.7%." (PMID 39400961, 2024).
type 2 diabetes (2 papers, 2007 to 2016). "The muscle glycogen synthase gene (GYS1) has been associated with type 2 diabetes (T2D), the metabolic syndrome (MetS), male myocardial infarction and a defective increase in muscle glycogen synthase protein in response to exercise." (PMID 17356695, 2007). "Circadian rhythmicity determined by JTK_CYCLE was found in gene expression of glycogen synthase 1 (GYS1) for type 2 diabetes patients only, but not for its inhibitory regulator – the glycogen synthase kinase 3 beta (GSK3b)." (PMID 27756900, 2016).
Alzheimer disease (1 paper, 2024). A progressive, neurodegenerative disease characterized by loss of function and death of nerve cells in several areas of the brain leading to loss of cognitive function such as memory and language. "For miR‐328‐5p, Gys1 (AMPK signaling pathway), Nos1 (Alzheimer's disease) and Pak6 (ErbB signaling pathway) were identified." (PMID 39317458, 2024).
Anxiety (1 paper, 2021). Intense feelings of nervousness, tension, or panic often arise in response to interpersonal stresses. "It was observed that the expressions of Gys1, Chka, Ncstn, and Ndufa6 were significantly down-regulated whereas Pgp, Klc1, and Kyat1 were up-regulated in the anxiety-susceptible group as compared to the control group." (PMID 33737865, 2021). "The results indicated that Atp6v1f, Arpc5, Adcyap1r1, Ndufb6, and Psmc6 were distinctly dysregulated in the hypothalamus of the depression-susceptible group, while Gys1, Pgp, Klc1, Chka, Ncstn, Ndufa6, and Kyat1 were distinctly dysregulated in the anxiety-susceptible group." (PMID 33737865, 2021).
Arthritis (1 paper, 2018). Inflammation of a joint. "Compared with normal rats, the arthritis index score and paw swelling (change in volume) were markedly increased in rats with CIA, whereas in GYS1-depleted rats, the arthritis index score and paw swelling were significantly reduced." (PMID 30100905, 2018). "Local joint depletion of GYS1 or intraperitoneal administration with an AMPK agonist ameliorated the severity of arthritis in rats with collagen-induced arthritis." (PMID 30100905, 2018).
Ataxia (1 paper, 2026). Ataxia refers to impaired coordination of voluntary muscle movement. "Gys1 deficiency in either PCs or GFAP-positive cells reduced anxiety-like behavior, whereas combined deletion caused PC degeneration and ataxia." (PMID 41890976, 2026).
Atrophy (1 paper, 2025). Any weakening or degeneration, especially through lack of use. "Muscle atrophy, observed in 11‐month‐old single Gaa KO mice, was less pronounced in the Gaa/Gys1 double KO mice, resulting in improved exercise capacity." (PMID 40268518, 2025).
bipolar disorder (1 paper, 2017). A disorder of the brain that causes unusual shifts in mood, energy, activity levels and the ability to carry out day-to-day tasks.
bladder urothelial carcinoma (1 paper, 2024). "In addition, a group of disulfidptosis-related genes (GYS1, LRPPRC, NDUFA11, OXSM, RPN1, SLC3A2, and SLC7A1) are found to influence the prognosis of bladder urothelial carcinoma via immune cell infiltration." (PMID 39701955, 2024).
breast tumors (1 paper, 2023). "These insights—along with a deeper mechanistic understanding of the long-term adaptations to GYS1 knockdown and induced sensitivity to mitochondrial inhibitors—will help to select breast tumors that are most susceptible to therapeutic targeting of glycogen metabolism." (PMID 37280675, 2023). "It is tempting to speculate that a similar glycogen-shunt between specific subsets of tumor cells with each other or surrounding cells from the tumor microenvironment could underlie the observed mosaic-like pattern of GYS1 and glycogen IHC expression in primary breast tumors." (PMID 37280675, 2023). "Immunohistochemical GYS1 expression in primary breast tumors was highest in TNBCs (median H-score 80, IQR 53–121) and other Ki67-high tumors (median H-score 85, IQR 57–124) (P < 0.0001)." (PMID 37280675, 2023). "The key glycogen synthesis enzyme GYS1 is expressed in most primary breast tumors, especially in triple-negative and Ki67-high tumors." (PMID 37280675, 2023). "mRNA expression of GYS1 and other glycogen-related enzymes in primary breast tumors and the correlation with patient survival were studied in the METABRIC dataset (n = 1904)." (PMID 37280675, 2023). "In short, GYS1 is expressed in the majority of primary breast tumors, with the highest levels in TNBCs and other Ki67-high tumors." (PMID 37280675, 2023). "To distinguish potential subgroups among breast tumors based on GYS1, glycogen and Ki67 scores, we performed unsupervised hierarchical clustering." (PMID 37280675, 2023).
cervical cancer (1 paper, 2024). A primary or metastatic malignant neoplasm involving the cervix. "We employed the cervical cancer cell lines HCC94 and CaSki by manipulating the expression of key enzymes PCK1, PYGL, and GYS1, which are involved in glycogen metabolism, through siRNA transfection." (PMID 38871968, 2024).
colon cancer (1 paper, 2023). "Consistent with our results obtained in colon cancer cell lines, Apc/Drp1-KO organoids exhibited a significant increase in GYS1 protein expression which coincided with an increase in AMPK and ACC phosphorylation." (PMID 37816729, 2023). "Similarly, increased GYS1 expression and glycogen accumulation are detected in xenograft tumors derived from Drp1 knockdown colon cancer cells." (PMID 37816729, 2023).
endometrial adenocarcinoma (1 paper, 2023). "ER-positivity did not clearly explain GYS1 expression levels, although recent studies in other cell types, e.g., endometrial adenocarcinoma cells and rat astrocytes, demonstrated that estradiol stimulates GYS1 expression." (PMID 37280675, 2023).
endometrial cancer (1 paper, 2020). Primary or metastatic malignant neoplasm involving the endometrium (mucous membrane that lines the endometrial cavity). "Next, in order to define the use of increased glucose uptake in endometrial cancer cells treated with LEFTY2, quantitative real-time PCR was utilized to determine GYS1 transcript levels." (PMID 32236143, 2020).
epilepsy (1 paper, 2024). A brain disorder characterized by episodes of abnormally increased neuronal discharge resulting in transient episodes of sensory or motor neurological dysfunction, or psychic dysfunction. "In particular, the Glycogen Synthase 1 (GYS1) gene stimulates glycogen biosynthesis, and its dysregulation has been associated with epilepsy in mouse models, impacting synaptic plasticity." (PMID 39057025, 2024).
hepatoma (1 paper, 2010). "Since GS activity is an absolute requirement for glycogen synthesis, we next investigated the effect of knocking down GYS1 in the hepatoma HepaC1 cells, which also express the liver isoform GYS2." (PMID 20300197, 2010).
ischemia (1 paper, 2020). A hypoperfusion of the BLOOD through an organ or tissue caused by a PATHOLOGIC CONSTRICTION or obstruction of its BLOOD VESSELS, or an absence of BLOOD CIRCULATION. "RNA-seq detected decreased GYS1 and GSK3Β in ischemic myocardium after prolonged ischemia, which may imply an additional mechanism exacerbating ischemic injury." (PMID 32223896, 2020).
lung carcinoma (1 paper, 2024). "The expression levels of NCKAP1 and GYS1 were examined in both lung cancer and normal alveolar epithelial cells." (PMID 38223725, 2024). "GYS1 is a pivotal rate-limiting enzyme that operates during the final stage of glycogen synthesis showed that GYS1 is upregulated in lung cancer cell lines following radiotherapy." (PMID 38223725, 2024). "However, the expression and role of NCKAP1 and GYS1 in lung cancer remain unclear." (PMID 38223725, 2024). "To investigate the functional roles of NCKAP1 and GYS1, we conducted experiments using the human lung cancer H460 cell line with knockdown of NCKAP1 and GYS1." (PMID 38223725, 2024). "The impact of SLC7A11 and SLC3A2 on the prognosis of lung cancer have been documented, it is still uncertain whether NCKAP1 and GYS1 influence the prognosis in lung cancer remains unclear." (PMID 38223725, 2024). "Our observations did not reveal any effect of GYS1 on lung cancer cell proliferation." (PMID 38223725, 2024).
metabolic myopathy (1 paper, 2021). A group of rare inherited disorders characterized by a deficiency of enzymes that are involved in metabolic pathways that affect muscles. "Finally, seven proteins were associated with metabolic myopathy where Cacna1s, Ampd1, Pygm, Gys1, and Pfkm were upregulated and where Gbe1 and Ca2 were downregulated." (PMID 34828261, 2021).
metabolic syndrome (1 paper, 2007). A cluster of metabolic risk factors for CARDIOVASCULAR DISEASES and TYPE 2 DIABETES MELLITUS. "A polymorphism (XbaI) in intron 14 of the glycogen synthase gene (GYS1) has been associated with lower glycogen synthase activity, T2D, features of the metabolic syndrome (MetS) and with myocardial infarction in males but association to T2D has not been consistently replicated in all studies." (PMID 17356695, 2007).
myocardial infarction (1 paper, 2007). Gross necrosis of the myocardium, as a result of interruption of the blood supply to the area, as in coronary thrombosis. "The GYS1 XbaI polymorphism was significantly associated with increased risk for CV mortality in males, a result supported by our previous independent finding of an association between myocardial infarction and this particular polymorphism only in males in another study population." (PMID 17356695, 2007).
myoclonus epilepsy (1 paper, 2010). "Moreover, recent findings demonstrate that the blockage of GYS1 degradation, caused by laforin or malin mutations, leads to increased glycogen levels in myoclonus epilepsy." (PMID 20300197, 2010).
papillary renal cell carcinoma (1 paper, 2020). A rare subtype of renal cell carcinoma, arising from the renal tubular epithelium and showing a papillary growth pattern, which typically manifests with hematuria, flank pain, palpable abdominal mass or nonspecific symptoms, such as fatigue, weight loss or fever. "In addition, glycogen storage and GYS1 expression differ between paired tumor and non-tumor samples in ccRCC, papillary renal cell carcinoma, and chromophobe renal carcinoma." (PMID 32802186, 2020).
rhabdomyolysis (1 paper, 2010). Necrosis or disintegration of skeletal muscle often followed by myoglobinuria. "Thirty six exertional rhabdomyolysis-susceptible horses were subsequently genotyped for the skeletal muscle glycogen synthase (GYS1) mutation responsible for type 1 polysaccharide storage myopathy." (PMID 20644724, 2010).
sarcoma (1 paper, 2024). A usually aggressive malignant neoplasm of the soft tissue or bone. "This study identified three valuable genes (SLC7A11, RPN1, GYS1) associated with disulfidptosis in sarcoma (SARC) and developed a prognostic model." (PMID 38531930, 2024). "Compared to their corresponding normal cell lines, SLC7A11, RPN1, and GYS1 exhibited significantly upregulated mRNA expression in sarcoma cell lines (143B, SW982, and SW872)." (PMID 38531930, 2024).
Stroke (1 paper, 2014). Sudden impairment of blood flow to a part of the brain due to occlusion or rupture of an artery to the brain. "Real-Time RT-PCR data revealed that mRNA expression levels of Gbe1, Gys1, and Pygb remained unchanged in contralateral and ipsilateral hemispheres of both sham and stroke rat brains at 6 and 24 hours time points (n = 5)." (PMID 24858129, 2014). "To assess whether ischemic insult alters the mRNA expression level of genes involved in glycogen metabolism we measured mRNA expression level of Gbe1, Gys1, Agl and Pygb in the contralateral and ipsilateral hemispheres of sham and stroke-affected rat brains." (PMID 24858129, 2014).